ALB (albumin)
Diseases named in the same sentence as ALB in open-access papers (continued):
Sharing a sentence is not in itself a finding about the gene and the disease.
steatosis (53 papers, 2008 to 2026). Increased lipid within the cytoplasm of cells. "Conversely, 6-day persistent steatosis initially induced by 24 h treatment with OA + PA caused reductions in the viability and albumin production in HepG2 steatosis OOCs." (PMID 37813918, 2023). "Pioglitazone improved the OOC viability while elafibranor reduced the steatosis in association with reduced viability and albumin production." (PMID 37813918, 2023). "In the first analysis, haemoglobin (p = 0.04), sodium (p = 0.003), AST (p = 0.01), ALT (p = 0.02), albumin (p < 0.0001), and severe steatosis at CAP (p = 0.03) were significantly associated with CEUS-PAT values." (PMID 36553020, 2022). "A decline in serum albumin concentration has been associated with steatosis in NAFLD patients." (PMID 39770467, 2024). "However, this anti-steatosis activity seemed to be specifically associated with adverse effects of elafibranor at 50 μM, as demonstrated by the reductions in cell viability and albumin production." (PMID 37813918, 2023). "Multivariate logistic analysis was conducted with age, sex, albumin, platelet count, history of appendectomy, and grade of steatosis (which showed significant associations on univariate analysis) as covariates and advanced fibrosis as the dependent variable in NAFLD patients." (PMID 27785221, 2013). "Intriguingly, when primary mouse hepatocytes were exposed to free fatty acids (FFAs) to induce steatosis, Usp25 protein levels were significantly lower than those in hepatocytes treated with bovine serum albumin." (PMID 39395794, 2024). "Serum albumin was higher in steatosis compared to the other two groups, potentially indicating decreased albumin formation in fibrosis due to the compromised liver parenchyma." (PMID 38738048, 2024). "Model score = 0.00592 + 0.86997 * AST − 0.40814 * ALT + 0.19083 * GGT − 0.32590 * ALB + 0.29954 * GLB + 0.31760 * (if steatosis) + 0.17445 * (if HbeAg positive) − 0.16393 * PLT." (PMID 37770837, 2023). "The response to albumin deficiency includes some changes in the lipoprotein profile but also beneficial changes (lower plasma FFA levels, lower steatosis, improved glucoregulation)." (PMID 37432201, 2023). "Although this analysis was not intended as a regression model to identify predictors for the CEUS-PAT results, we found associations worth further exploration, such as haemoglobin, sodium, AST, ALT, albumin, and severe steatosis at CAP." (PMID 36553020, 2022). "Single regression analysis showed that sex (p = 0.027), BMI (p = 0.040), albumin (p = 0.002), pathological steatosis (p = 0.006), pathological ballooning (p = 0.011), and SCD (p < 0.001) were significantly associated with the CAP." (PMID 34341368, 2021). "For the PA-induced steatosis cell model, the cells were treated with 0.3 mM PA conjugated with serum-free bovine albumin for 24 h." (PMID 32992548, 2020). "Histological steatosis remained more pronounced and albumin reduced in αYap1‐siRNA‐treated animals, reflecting an impaired function—likely because of the still smaller remnant relative to controls at 48 hours." (PMID 30740593, 2019). "Multivariate logistic analysis was conducted with age, sex, albumin, platelet count, steatosis grade, and history of appendectomy as covariates and advanced fibrosis as the dependent variable." (PMID 27785221, 2013). "Albumin levels were 38.1 ± 2.3 g/dl in the control group, 40.54 ± 1.87 g/dl in the steatosis group, and 41.1 ± 2.9 g/dl in the resveratrol group (P < 0.05 between control group vs steatosis and resveratrol groups)." (PMID 18782455, 2008). "Low levels of albumin, increased amounts of bilirubin, and changes in clotting factors may also indicate liver problems, which can help diagnose steatosis." (PMID 39458995, 2024). "Consistently, persistent steatosis caused no significant reductions in albumin production in HepG2 OOCs exposed to OA as compared to those exposed to Veh." (PMID 37813918, 2023).
steatosis (continued). "Multivariate regression showed that waist-to-hip ratio, fibroblast growth factor (FGF) 21, FGF19, adiponectin-to-leptin ratio, insulin, albumin, triglyceride, total-cholesterol, and alanine-aminotransferase were independent predictors of steatosis (rank-ordered by Wald)." (PMID 35663311, 2022). "Nonetheless, B-13/H cells will accumulate intracellular triglycerides in the form of lipid droplets (steatosis) in response to exposure to high levels of medium fatty acids (bound to albumin to reduce their toxicity) or when exposed to the LXR activator T0901317." (PMID 28552552, 2017). "It is possible that during hepatocytes steatosis, inflammation response, or viral infection, the three-dimensional structure of the albumin molecule is altered, leading to the structural changes on its metal ion binding site and the reduction of its ion binding capacity." (PMID 28101103, 2016). "HepG2 steatosis OOCs offer a drug efficacy and toxicity testing platform to assess whether compounds of interest can improve or exacerbate steatosis, cell damage, and albumin production." (PMID 37813918, 2023). "Therefore, we examined whether three major drug candidates for NAFLD/NASH alleviated fat accumulation and reductions in viability and albumin production in HepG2 steatosis OOCs." (PMID 37813918, 2023). "Univariate analysis revealed age, BMI, AST, ALB, ALP, TG, and high-calorie diet as significant variables (p < 0.05) across inflammation, steatosis, and fibrosis subgroups." (PMID 42089068, 2026). "Persistent steatosis-mediated reductions in OOC viability and albumin production were deteriorated by elafibranor." (PMID 37813918, 2023). "Using the same method, BMI, ALT/AST, albumin, cholesterol, triglycerides, CTL-S and CTL/S were found to be significantly relevant to moderate-severe steatosis in Group two." (PMID 37021007, 2023). "While ALP, ALB, BUN, serum TG, hepatic TG, Col-1a1 and hallmarks of liver function (such as fibrosis, steatosis, ballooning, inflammation and NAS Score) were significantly correlated to the differential metabolites." (PMID 34200685, 2021). "The second cluster exhibited markers that had similar levels between the groups with mild or moderate/severe steatosis, with increased levels of hemoglobin, GGT, and albumin." (PMID 32498337, 2020). "Factors that show significant difference between groups (p < 0.05) included: height, BMI, original liver volume, ALT, albumin, AST, creatinine, GGT, platelet, INR, steatosis, spleen volume, and glucose." (PMID 25593935, 2014). "Steatosis is most commonly induced by a combination of high carbohydrate levels (glucose with or without fructose), high levels of insulin and albumin‐conjugated free fatty acids (FFAs), typically oleic and palmitic acid." (PMID 41200938, 2025). "In the 5-fluorouracil-treated group focal steatosis, serum AST, ALT, ALP and ALB levels were markedly decreased in rats treated with 5-fluorouracil (20 mg/kg) (P < 0.001), inflammatory cell infiltration and hepatocellular damage were observed, suggesting liver injury." (PMID 38319413, 2024). "In contrast, 24 h exposure to OA, followed by maintaining persistent steatosis for 6 days had no negative impact on the viability and albumin production in HepG2 OOCs." (PMID 37813918, 2023). "Consistently, 6-day treatment with metformin exerted no beneficial effects on fat accumulation, viability, and albumin production in HepG2 steatosis OOCs." (PMID 37813918, 2023). "Moreover, persistent steatosis for 6 days impaired OOC viability and hepatic function, as measured by a WST-8 assay and albumin production, respectively." (PMID 37813918, 2023). "Resveratrol and NAC administration significantly improved liver index (resveratrol only), alanine transaminase, TNF-α, glucose, albumin, malondialdehyde (MDA), GSH, glutathione-S-transferase, total cholesterol, low-density lipoprotein-c, and leptin levels compared with steatosis control values." (PMID 33339155, 2020).
steatosis (continued). "Albumin production was slightly decreased in steatosis-induced spheroids but not in HET0016-treated steatosis spheroids." (PMID 31406506, 2019). "Similarly, metformin did not affect OOC viability and albumin production, both of which were reduced by the 6-day persistent steatosis." (PMID 37813918, 2023). "We also found that the levels of clinical variables including albumin, creatinine, and creatine kinase as well as the amount of fat‐free mass in right arm were significantly higher in subjects with severe steatosis but not in subjects with moderate and mild steatosis, compared with no steatosis." (PMID 35128832, 2022). "In chronic HCV with steatosis, elevated AFP levels correlated positively with HAI and negative significant correlation with albumin level." (PMID 22675639, 2012). "In our study a negative correlation was found between lower serum albumin and AFP among patients with steatosis." (PMID 22675639, 2012).
lupus (50 papers, 2008 to 2025). "SLE patients with older age of onset, low serum albumin levels, and high cystatin C levels are at higher risk for readmission due to infections and lupus activity." (PMID 39650958, 2024). "Furthermore, data from the NYU Specimen and Matched Phenotype Linked Evaluation (SAMPLE) Lupus Registry demonstrated that, in lupus nephritis, serum ALB levels >3.7 g/dL at 12 months of follow-up after renal biopsy predicted good long-term renal outcome." (PMID 37762957, 2023). "ACR serves as a clinical marker of renal involvement, a frequent and severe complication of lupus, with elevated urinary albumin excretion signifying glomerular damage and compromised kidney function." (PMID 39940777, 2025). "Given the positive lupus serology and the 24 h urine protein of 0.54 g/day with serum albumin of 24 g/L (ref: 37–47 g/L), a renal biopsy was decided to delineate any evidence of organ involvement in active lupus." (PMID 39734638, 2024). "The standard biochemical profile in lupus patients often includes a measurement of serum albumin, which can be low in these patients." (PMID 38961124, 2024). "Both types of antibodies seemed to negatively influence the total protein and albumin levels in systemic lupus erythematosus." (PMID 39768675, 2024). "The basic anti-ETAR antibodies correlated negatively with the total protein level after 3 months (p = 0.03) and with the albumin level after 3 (p = 0.01) and 6 months (p = 0.03) of observation in the systemic lupus erythematosus group." (PMID 39768675, 2024). "Systemic lupus erythematosus mice had significantly higher albumin excretion compared to control mice at 34 weeks of age measured by ELISA (two‐way ANOVA, group effect)." (PMID 32652896, 2020). "The results of this research illustrated that urinary albumin dramatically decreased in lupus mice after JP intervention." (PMID 32760274, 2020). "We added octreotide or two different preparations of albumin to either APS-IgG or control IgG preparations [from a patient with systemic lupus erythematosus (SLE) or a healthy subject]." (PMID 30405613, 2018). "In addition, a statistically significant correlation was observed between the initial plasma PAR 1 concentration and the initial serum albumin concentration in the systemic lupus erythematosus cohort (n = 22; p = 0.05; r = 0.42)." (PMID 41517469, 2025). "The proportion of patients achieving a complete response was similar in both groups, along with similar improvements in serum albumin, complement, kidney function, systemic lupus erythematosus disease activity index and the British Isles Lupus Assessment Group score." (PMID 39759531, 2024). "The anti-CXCR3 antibody level correlated negatively with the total protein level after 2 years of observation (p = 0.03) and with the basic albumin level (p = 0.02) and albumin level after 1 month of observation (p = 0.04) in the systemic lupus erythematosus group." (PMID 39768675, 2024). "As a prominent characteristic of lupus, the albumin level decreased with HCQ treatment." (PMID 35705919, 2022). "Compared to LN patients without HUA, we found that LN patients with HUA presented with higher BP and triglyceride levels; lower hemoglobin and serum albumin levels; worse renal function, hematuria, and proteinuria; higher activity of lupus; and more positive antiphospholipid antibody." (PMID 35683463, 2022). "Compared to LN patients without HUA, LN patients with HUA presented with higher blood pressure and triglyceride levels, lower hemoglobin and serum albumin levels, worse renal function, worse hematuria and proteinuria, higher lupus activity, and more positive antiphospholipid antibody." (PMID 35683463, 2022). "Compared to patients without HUA, those with HUA presented with higher blood pressure and triglyceride levels, lower hemoglobin and serum albumin levels, worse renal function, more severe hematuria and proteinuria, higher lupus activity, and more positive antiphospholipid antibody." (PMID 35683463, 2022).
lupus (continued). "Additionally, both the elevated levels of urinary albumin (OR = 0.996, 95% CI: 0.993–0.999) and urinary iodine (OR = 0.96, 95% CI: 0.95–0.97) were protective against lupus." (PMID 32537455, 2020). "Crescent group had higher serum creatinine, lower serum albumin, higher systemic lupus erythematosus (SLE) disease activity index, and higher activity index of renal tissue." (PMID 36732805, 2023). "In a cohort of 1078 patients diagnosed with SLE, serum ALB concentration inversely correlated to overall SLE disease activity, especially in those suffering from lupus nephritis and proteinuria." (PMID 37762957, 2023). "This is different from what happens in systemic lupus erythematosus and other inflammatory diseases, where TNF-α levels go up as albumin levels go down." (PMID 41011058, 2025). "Lupus-prone mice were grouped based on albumin-to-creatinine ratio (ACR), total IgG, and IgG2a levels, which are well-established biomarkers of lupus severity." (PMID 39940777, 2025). "SLEDAI showed statistical differences between the two groups after treatment (p < 0.01), while complement C4, ALB, and GFR showed statistical differences before and after treatment in the lupus group (p < 0.01)." (PMID 38628865, 2024). "The results of this study showed that after treatment in the lupus and synbiotic groups, the values of SLEDAI, 24-h urine protein, WBC count, and other indicators decreased, whereas the values of ALB, HB, GFR, and other indicators increased." (PMID 38628865, 2024). "There was also a positive correlation between CST6 with Systemic Lupus Erythematosus Disease Activity Index (SLEDAI) and CST6 with albumin in CSF." (PMID 37684700, 2023). "There were some differences in Systemic Lupus Erythematosus Disease Activity Index (SLEDAI), Creatinine (Cr), Blood Urea Nitrogen (BUN), C3, C4, and Albumin (Alb) among various ISN/RPS class LN patients." (PMID 35572531, 2022). "Statistical analysis was conducted to assess the efficacy (proteinuria, systemic lupus erythematosus disease activity index (SLEDAI), Scr, BUN, albumin, C3, and C4) and safety (rate of adverse events) of MSCs for SLE using Cochrane Review Manager Version 5.3." (PMID 32322279, 2020). "The current study seeks to better characterize the repertoire and stoichiometry of albumin citrullination sites in RA by mass spectrometry and to assess ACPA reactivity at each site compared with healthy control (HC) and systemic lupus erythematosus patients as a disease control." (PMID 40609794, 2025). "Both types of antibodies seem to have a negative influence on total protein and albumin levels in systemic lupus erythematosus." (PMID 39768675, 2024). "However, Dorraji and colleagues were able to visualize TLS in the pancreas of lupus-prone, anti-dsDNA antibody positive, NZB/NZW F1 mice by single photon emission computed tomography (SPECT) using 99mTC labeled Albumin Nanocoll." (PMID 38022566, 2023). "Unsurprisingly, our results revealed that IL-6 and IL-1β cytokine levels in the hippocampus of lupus mice were significantly higher than those in the control mice, with albumin accumulation in situ (data not shown)." (PMID 34645459, 2021). "Our study also found that the elevated levels of serum bicarbonate, creatinine, serum vitamin B12, urinary albumin and iodine may be protective factors against SLE, while serum chloride, globulin, lactate dehydrogenase, and uric acid may be risk factors for lupus." (PMID 32537455, 2020). "Serum albumin, a readily-available, routine measurement in SLE, has shown a negative association with disease activity in lupus patients." (PMID 30884776, 2019). "This study is the first to show that the intracellular biomarker miR-146a-5p may serve as a useful specific biomarker for the detection of lupus nephritis among lupus patients in the future, regardless of serum albumin levels and spot urine protein/creatinine ratio." (PMID 29963250, 2018).